ZCWPW2 (zinc finger CW-type and PWWP domain containing 2)
Description:
Histone methylation reader which binds to non-methylated (H3K4me0), monomethylated (H3K4me1), dimethylated (H3K4me2) and trimethylated (H3K4me3) 'Lys-4' on histone H3. The order of binding preference is H3K4me3 > H3K4me2 > H3K4me1 > H3K4me0.
Synonyms: ZCW2
Tractability: No criterion of Open Targets' tractability assessment is met for any kind of drug.
Gene: Protein-coding gene on chromosome 3 (28,348,721 to 28,538,122, forward strand). Ensembl gene ENSG00000206559.
Subcellular location (Human Protein Atlas): Nuclear speckles
Gene Ontology:
Molecular function: histone H3K4me3 reader activity; protein binding; zinc ion binding
Biological process: chromatin organization
Cellular component: nucleus
Genetic constraint (gnomAD): Loss-of-function variants: 37 observed, 36.67 expected, observed/expected ratio (o/e) 1.01, 90% interval 0.77 to 1.33. The upper end of that interval is the gene's LOEUF score, 1.33, which puts it in group 5 of 6, group 1 being the genes least tolerant of losing a copy. Missense variants: 336 observed, 332.36 expected, observed/expected ratio (o/e) 1.01, 90% interval 0.92 to 1.11. Synonymous variants: 115 observed, 115.09 expected, observed/expected ratio (o/e) 1, 90% interval 0.86 to 1.17.
Homologues: Orthologues: chimpanzee ZCWPW2 (97% identical), macaque ZCWPW2 (94% identical), pig ZCWPW2 (84% identical), rabbit ZCWPW2 (80% identical), dog ZCWPW2 (73% identical), mouse Zcwpw2 (61% identical), rat Zcwpw2 (58% identical). Paralogues in human: ZCWPW1 (21% identical).
Diseases named in the same sentence as ZCWPW2 in open-access papers:
ZCWPW2 is named in the same sentence as 4 diseases in open-access papers, as found by Europe PMC text mining. Sharing a sentence is not in itself a finding about the gene and the disease. The quoted sentences say what the papers report.
cancer (1 paper, 2022). A tumor composed of atypical neoplastic, often pleomorphic cells that invade other tissues. "Among them, PRDM16, SETDB2, SGF29, and ZCWPW2 were protective genes and were all downregulated in the tumor samples, while the others were enriched in the cancer tissues and were associated with poor prognosis." (PMID 36263018, 2022).
tumor (1 paper, 2022). "We confirmed that SETDB2 (HR: 0.773, 95%CI: 0.640–0.932), SGF29 (HR: 0.918, 95%CI: 0.860–0.979), PRDM16 (HR: 0.891, 95%CI: 0.807–0.983), CBX7 (HR: 0.906, 95%CI: 0.833–0.986), and ZCWPW2 (HR: 0.325, 95%CI: 0.117–0.901) were protective genes, and they were all downregulated in the tumor samples." (PMID 36263018, 2022).
ZCWPW2 also shares sentences with these, for which no sentence is quoted: infection (1 paper); Obesity (1).